PIGR (polymeric immunoglobulin receptor)
Diseases named in the same sentence as PIGR in open-access papers (continued):
Sharing a sentence is not in itself a finding about the gene and the disease.
Sepsis (3 papers, 2014 to 2025). Sepsis is defined as life-threatening organ dysfunction caused by a dysregulated host response to infection. "In this study, we investigated the association of plasma pIgR with the diagnosis, prognosis and pathogenesis of sepsis." (PMID 40642082, 2025). "The role and underlying mechanisms of plasma pIgR were investigated in mouse models of sepsis and primary alveolar type 2 epithelial cells (AT2)." (PMID 40642082, 2025). "Given that sepsis is most commonly developed from pneumonia, this study focused on the association of plasma pIgR with sepsis in PIS subjects." (PMID 40642082, 2025). "In this study, we find that plasma pIgR is a potential prognostic biomarker for pneumonia-induced sepsis and contributes to the lethality of sepsis caused by different infections." (PMID 40642082, 2025). "Future studies should determine the association of plasma pIgR with the occurrence and prognosis of sepsis caused by infections at other organs." (PMID 40642082, 2025). "Although the effects of r_pIgR and pIgR_Ab on the mortality of CLP mice suggest that plasma pIgR may also participate in the pathogenesis of sepsis caused by different infections, the underlying mechanisms remain to be elucidated." (PMID 40642082, 2025). "The association of plasma pIgR with sepsis mortality raised the possibility that the elevation of plasma pIgR may contribute to sepsis lethality." (PMID 40642082, 2025). "Together with observations in KPS mice, these results suggest that plasma pIgR contributes to the lethality of sepsis induced by infections at different organs." (PMID 40642082, 2025). "In light of the prevalence of KP infection in sepsis patients, KPS model was used to characterize the role of plasma pIgR in sepsis pathogenesis." (PMID 40642082, 2025). "In this study, we characterized the association of plasma pIgR with the occurrence and prognosis of sepsis induced by pneumonia, and examined the role of plasma pIgR in the pathogenesis of pneumosepsis induced by pulmonary KP infection." (PMID 40642082, 2025). "The key findings include that the level of plasma pIgR is associated with the prognosis of PIS patients and that plasma pIgR aggravates the lethality of sepsis induced by pulmonary KP infection and peritoneal polymicrobial infection." (PMID 40642082, 2025). "pIgR-neutralizing antibody (pIgR_Ab) exhibited opposite effects on animal survival in both sepsis models and on the injury score, caspase-11 and GSDMD-NT." (PMID 40642082, 2025). "In current study, the effects of intravenous administrations of r_pIgR on the survival of both KPS and CLP mice provide a strong support of a detrimental role of plasma pIgR in sepsis." (PMID 40642082, 2025). "This study demonstrates that plasma pIgR is a potential prognostic marker for sepsis, and likely contributes to AT2 pyroptosis and sepsis lethality through interaction with IgM, indicating a broad pro-pathogenic role of plasma pIgR in infectious diseases." (PMID 40642082, 2025). "Observed effects of r_pIgR and pIgR_Ab should be confirmed using materials of human origin in the future., which help validify the usefulness of pIgR antibody-based strategies for the treatment of sepsis." (PMID 40642082, 2025). "This hypothesis should be thoroughly tested in future in vitro and in vivo studies, which would help clarify molecular details of the mechanism underlying the detrimental role of plasma pIgR-IgM immune complex in AT2 injury and sepsis pathogenesis." (PMID 40642082, 2025). "Moreover, characterizations of the role of plasma pIgR in sepsis were conducted using mouse sepsis models and primary mouse AT2 cells in this study." (PMID 40642082, 2025). "On the other hand, disrupting the interaction between plasma pIgR and pIgs may be a useful strategy for the development of sepsis therapy." (PMID 40642082, 2025).
Sepsis (continued). "In contrast to pIgR, the level of J-chain peptides, which reflects the level of pIgs, was not significantly different between moderate and moribund plasma (p = 0.875), suggesting that the deterioration of sepsis is associated with increased pIgR, but not pIgs, in the blood." (PMID 40642082, 2025). "In light of the protective effect of pIgR_Ab in both KPS and CLP sepsis models, pIgR-neutralizing antibodies targeting the binding site(s) of IgM and dIgA may have the potential for the treatment of sepsis that claims approximately 11 million human lives annually worldwide." (PMID 40642082, 2025). "We next examined the effect of plasma pIgR on the survival of CLP mice, the most commonly used model of polymicrobial sepsis." (PMID 40642082, 2025). "Intravenous administrations of recombinant pIgR (r_pIgR) increased the mortality in mouse models of Klebsiella pneumoniae (KP)-induced pneumosepsis (KPS) and polymicrobial sepsis." (PMID 40642082, 2025). "We did not observe any difference in the serum IL17 levels and the survival rate between pIgR+/+ and pIgR−/− mice following CLP, suggesting that circulating IgA plays a key role in the protection against sepsis." (PMID 30737385, 2019). "On the other hand, the association of elevated plasma pIgR with multiple organ failures is in agreement with observations that pIgR level is higher in the moribund than moderate phase of sepsis, as shown by the TMT-MS analysis, and in non-survivors than survivors." (PMID 40642082, 2025). "In addition to ARDS and sepsis (this study), an elevation of plasma pIgR also occurs in several non-infectious (sterile) chronic inflammatory diseases." (PMID 40642082, 2025).
adenoma (2 papers, 1996 to 2020). A neoplasm arising from the epithelium. "SC mRNA was detected in all adenomas, and only two of ten carcinomas (10.5%) deemed to be SC deficient by immunohistochemistry also lacked SC mRNA expression, suggesting diallelic alterations in the SC-encoding gene (locus PIGR)." (PMID 8664120, 1996).
atherosclerosis (2 papers, 2025 to 2026). A disease characterized by the build-up of fatty material and calcium deposition in the arterial wall resulting in partial or complete occlusion of the arterial lumen. "Circulating PIGR, largely derived from cleaved secretory fragments, may contribute to immune regulation and serve as a biomarker of subclinical atherosclerosis and CVD." (PMID 41356597, 2025).
diabetes (2 papers, 2015 to 2022). "To begin investigating the effect of pIgR upon diabetes pathogenesis, we introduced a Pigr null allele generated in C57BL/6 (B6) mice onto the NOD genetic background." (PMID 25835383, 2015). "These pIgR-deficient NOD mice exhibited increased serum IgA along with an increased diabetes incidence." (PMID 25835383, 2015).
glioma (2 papers, 2020 to 2024). A benign or malignant brain and spinal cord tumor that arises from glial cells (astrocytes, oligodendrocytes, ependymal cells). "Additionally, expression of PIGR has been identified as a novel predictor of poor glioma patient prognosis after surgical resection." (PMID 32922940, 2020).
head and neck squamous cell carcinoma (2 papers, 2022 to 2026). A squamous cell carcinoma that arises from any of the following anatomic sites: lip and oral cavity, nasal cavity, paranasal sinuses, pharynx, larynx, and salivary glands. "Recently, a study showed that siRNA-mediated silencing of LAMB3 could enhance the sensitivity of head and neck squamous cell carcinoma cells to cisplatin, which may explain why PIGR can also increase the sensitivity of CRC cells to cisplatin." (PMID 35992840, 2022).
hepatitis B (2 papers, 2014). "pIgR was identified as a prognostic biomarker for HCC and was shown to have a role in the hepatitis B infection, chronic liver inflammation, the induction of the epithelial-mesenchymal transition, HCC recurrence and metastatic progression." (PMID 24699841, 2014).
IgA nephropathy (2 papers, 2017 to 2021). "We and others have also linked urinary polymeric immunoglobulin receptor fragments to severity of kidney injury in patients with CKD in the context of cardio-renal syndrome and IgA nephropathy." (PMID 34287333, 2021). "Both PIGR and FCAMR are implicated in IgA nephropathy, a condition where IgA immune complexes are deposited in the glomerular mesangium." (PMID 28355232, 2017).
influenza (2 papers, 2011 to 2022). An acute viral infection of the respiratory tract, occurring in isolated cases, in epidemics, or in pandemics; it is caused by serologically different strains of viruses (influenzaviruses) designated A, B, and C, has a 3-day incubation period, and usually lasts for 3 to 10 days. "Influenza infection was found to increase receptors that promote bacterial adhesion, such as polymeric immunoglobulin receptor and fibronectin leucine-rich transmembrane protein 1 in cardiomyocytes." (PMID 35089061, 2022). "We also measured the influenza-specific pIgR concentrations in nasal washes and saliva by ELISA to confirm that the IgA was locally produced (sIgA) rather than a transudate from serum." (PMID 22069479, 2011).
Insulin resistance (2 papers, 2021 to 2023). Increased resistance towards insulin, that is, diminished effectiveness of insulin in reducing blood glucose levels. "In an early effort, we identified polymeric immunoglobulin receptor (PIGR) as a predictor of NAFLD independent of insulin resistance, and this association between PIGR and NAFLD was subsequently reproduced in other studies." (PMID 34682795, 2021).
liver cirrhosis (2 papers, 2019 to 2021). "PIGR is a particularly promising protein as its association with NAFLD and liver cirrhosis is novel, and its levels in plasma are highly correlated with DPP4, a widely used drug target in the treatment of T2D." (PMID 30824564, 2019).
liver disease (2 papers, 2019 to 2022). "Remarkably, in this unbiased analysis, four clinical markers used in liver disease—ALT, AST, ALP, and GGT—clustered into a single group together with a panel of five proteins of special interest—PIGR, DPP4, ANPEP, TGFBI, and APOE." (PMID 30824564, 2019).
lymph node metastasis (2 papers, 2014 to 2021). "The IL-1RN rs419598 wild-type genotype was significantly related to stage III-IV disease, the PIGR rs291102 wild-type genotype was significantly related to normal levels of CYFRA, and the BCL2 rs2279115 wild-type genotype was significantly related to lymph node metastasis." (PMID 34150619, 2021). "The IL-1RN rs419598 wild-type genotype was significantly related to stage III-IV disease, the PIGR rs291102 wild-type genotype was significantly related to normal levels of cytokeratin fragment 19 (CYFRA), and the BCL2 rs2279115 wild-type genotype was significantly related to lymph node metastasis." (PMID 34150619, 2021).
periampullary adenocarcinoma (2 papers, 2014 to 2025). An adenocarcinoma that arises from the periampullary region. "The mechanistic basis underlying the potential tumour-suppressing role for pIgR in pancreatic and periampullary adenocarcinoma, as well as in several other cancer forms, remains to be elucidated." (PMID 25397670, 2014). "This is, to the best of our knowledge, the first study on the prognostic value of pIgR expression in pancreatic and periampullary adenocarcinoma." (PMID 25397670, 2014). "Here, we examined the expression and prognostic significance of pIgR in pancreatic and periampullary adenocarcinoma." (PMID 25397670, 2014). "The aim of this study was therefore to examine the expression of pIgR, and its prognostic impact, in primary tumours and paired lymph node metastases from a consecutive cohort of patients surgically treated with pancreaticoduodenectomy (PD) for pancreatic and periampullary adenocarcinoma (n = 175)." (PMID 25397670, 2014). "It is therefore reasonable to assume that the role of pIgR in carcinogenesis and tumour progression may well differ by histological type and tumour origin, which should be considered in future translational studies on pancreatic and periampullary adenocarcinoma." (PMID 25397670, 2014).
pneumonia (2 papers, 2014 to 2025). An acute, acute and chronic, or chronic inflammation focally or diffusely affecting the lung parenchyma, caused by an infection in one or both of the lungs (by bacteria, viruses, fungi, or mycoplasma.). "In addition, pneumococcal binding to pIgR and PAFR may facilitate the development of bacteremic pneumonia." (PMID 24691515, 2014). "Nevertheless, the reported concentration of plasma pIgR is in line with our finding in PIS patients, which is not unexpected given that ARDS most commonly develops from pneumonia and non-pulmonary sepsis." (PMID 40642082, 2025).
varicocele (2 papers, 2020 to 2021). A condition characterized by the dilated tortuous veins of the spermatic cord with a marked left-sided predominance. "PIGR is involved in the tissue homeostasis pathway and its expression is regulated by cytokines, which show high levels in the seminal plasma of varicocele patients due to an inflammatory response." (PMID 34336830, 2021).
vasculitis (2 papers, 2020 to 2025). "A recent study described increased PIGR and IGA expression in the aorta in a vasculitis model in mice." (PMID 40624587, 2025). "However, the differences between the mean amplitude of pIgR-peptides in healthy controls and CKDs differs significantly only with the disease groups IgAN, FSGS, vasculitis, nephritis, nephrosclerosis, DKD, and all other CKDs." (PMID 32427855, 2020).
AIDS (1 paper, 2017). A syndrome resulting from the acquired deficiency of cellular immunity caused by the human immunodeficiency virus (HIV). "Further studies are warranted to reveal the mechanism underlying the decrease of pIgR expression in HIV/AIDS." (PMID 28271669, 2017). "Although increased respiratory colonization and infections are common in HIV/AIDS, little is known about the expression of pIgR in the airway mucosa of these patients." (PMID 28271669, 2017). "The reduced expression of pIgR might be the underlying mechanism of increased pulmonary microbiota and infections in HIV/AIDS." (PMID 28271669, 2017). "To determine whether pIgR is involved in the respiratory pathology of HIV/AIDS, we examined the expression of pIgR in the tracheal mucosa of SHIV/SIV-infected rhesus macaques." (PMID 28271669, 2017). "Since elevated microbes can drive the COPD-like phenotype in pIgR deficient mice and downregulation of pIgR is observed in COPD patients, reduced pIgR expression could be an underlying mechanism of the increased incidence of COPD in HIV/AIDS patients." (PMID 28271669, 2017).
alcoholic fatty liver disease (1 paper, 2021). Lipid infiltration of the hepatic parenchymal cells that is due to alcohol abuse. "It was reported that the expression of pigR was significantly upregulated together with the secretion of IgA in the intestinal inflammatory conditions caused by non-alcoholic fatty liver disease, which is consistent with our results." (PMID 34616764, 2021).
Allergy (1 paper, 2020). An allergy is an immune response or reaction to substances that are usually not harmful. "Lactoferrin (80 kDa), monocyte differentiation antigen CD14 (56 kDa), polymeric immunoglobulin receptor (83 kDa), and lactadherin (~50 kDa) are some examples of proteins often mentioned in relation to the allergy-protective effect of raw cow’s milk, that fall within the molecular weight range." (PMID 32438725, 2020).
Anxiety (1 paper, 2021). Intense feelings of nervousness, tension, or panic often arise in response to interpersonal stresses. "Proteomic analysis of salivary proteins unveiled a different pattern of responses after the test anxiety task in control and odor groups, with the exception of α-amylase, PIGR, and IgA, which showed comparable expression changes." (PMID 33919012, 2021).
Autoimmunity (1 paper, 2023). The occurrence of an immune reaction against the organism's own cells or tissues. "Subsequently, its loss of tolerance induces pIgR-specific humoral and T cell autoimmunity that produces anti-pIgR autoantibodies and recruits pIgR antigen- specific CD27+ memory B and plasma cells to the hepatic portal tracts." (PMID 36759512, 2023).
bacteremia (1 paper, 2014). "After intranasal challenge, mice lacking pIgR showed less nasal colonization and decreased levels of bacteremia compared to wild-type mice but, unfortunately, no data was provided on the presence of the bacteria in the brain and or CSF." (PMID 24841255, 2014).
bladder tumors (1 paper, 2023). "Our genetic results demonstrate that CG does not have the classic chromosomal variation observed in bladder tumors, reveal the specific effects of TNF in KRT15 epithelial cells, and identify a new population of PIGR epithelial cells with high immunogenicity." (PMID 36814917, 2023).
Chronic colitis (1 paper, 2022). A chronic inflammatory disease of the large intestine (colon, cecum and rectum). "The expression of pIgR was reduced in the colonic epithelial cells of both DSS induced acute colitis and T-cell induced chronic colitis of mouse models." (PMID 35493520, 2022).
chronic kidney disease (1 paper, 2020). Impairment of the renal function secondary to chronic kidney damage persisting for three or more months. "Furthermore, they demonstrated that during chronic kidney disease (CKD) the expression of pIgR in the tubules becomes prevalent, associated with increased levels of urinary secretory immunoglobulins." (PMID 32427855, 2020).
colon adenocarcinoma (1 paper, 2022). "The scatter plot from TIMER database further demonstrated that the expression level of PIGR was strongly positively correlated with B cell in colon adenocarcinoma (COAD) and rectum adenocarcinoma (READ) patients." (PMID 36157233, 2022).
colorectal adenocarcinoma (1 paper, 2022). The most common type of colorectal carcinoma. "We explored the coexpression network and biological functions of PIGR in the TCGA-Colorectal adenocarcinoma (COADREAD) cohort." (PMID 36157233, 2022).
coronary artery disease (1 paper, 2020). "In conclusion, based on data focussing on urinary peptides in a large cohort of almost 3000 individuals, this study supports recent findings that pIgR is correlated with changes in kidney function and with an association to coronary artery disease." (PMID 32427855, 2020). "Due to the fact that heart and kidneys are involved in maintaining hemodynamic stability and organ perfusion through an intricate network, the pIgR might also be associated to coronary artery diseases (CAD)." (PMID 32427855, 2020). "Furthermore, pIgR peptides were significantly increased in cardiovascular disease (coronary artery disease and heart failure) after adjustment for eGFR." (PMID 32427855, 2020).
Crohn disease (1 paper, 2024). A gastrointestinal disorder characterized by chronic inflammation involving all layers of the intestinal wall, noncaseating granulomas affecting the intestinal wall and regional lymph nodes, and transmural fibrosis. "The decrease of pIgR has been confirmed in the colonic mucosa of both Crohn’s disease (CD) and UC patients." (PMID 39188786, 2024).
ductal carcinomas (1 paper, 2007). "In particular, transcription regulators (ATF3, PIGR), genes encoding proteins with cytokine and growth factor activity (PTN, CX3CL1) and genes encoding proteins involved in ion transport and metabolism (ATP1A2, MMP7) were downregulated in ductal carcinomas when compared with normal cells." (PMID 17389037, 2007).
endometrial tumor (1 paper, 2022). "The imaging data in this study consisted of 210 tissue microarray (TMA) cores from endometrial tumor samples stained for plasma cells, B cells, IgA, IgG, and pIgR." (PMID 35845830, 2022).
escherichia coli infection (1 paper, 2022). Infection with the organism Escherichia Coli. "Urinary PIGR has been detected decreased significantly in systemic Escherichia coli infection in mice." (PMID 36585464, 2022).